BRAF (B-Raf proto-oncogene, serine/threonine kinase)
Diseases named in the same sentence as BRAF in open-access papers (continued):
Sharing a sentence is not in itself a finding about the gene and the disease.
melanoma (continued). "Given many BRAF-mutated melanoma patients experience disease progression with targeted BRAF inhibitors, we hypothesized therapeutic response is related to tumor metabolic phenotype, and that altering tumor metabolism could change therapeutic outcome." (PMID 28205616, 2017). "Patients whose melanoma expresses V600 mutated BRAF may receive therapy with BRAF and MEK inhibitors." (PMID 28807052, 2017). "Several studies have investigated the prognostic role of BRAF mutations in melanoma, but it remains unclear." (PMID 29176861, 2017). "In patients with BRAF V600E-mutated melanoma, the individual EZH2 gain status should be tested first, and cotreatment with BRAF and EZH2 inhibitors can be applied to patients containing EZH2 gain and BRAF V600E mutation simultaneously to enhance the anticancer effects." (PMID 29202777, 2017). "Mutations in BRAF are the most common targetable genetic variant in advanced melanoma." (PMID 29179523, 2017). "However, inhibition of BRAF in a murine model of human melanoma was associated with decreased tumor-resident lymphocytes and resistance to CTLA-4 mAb." (PMID 28659921, 2017). "Indeed, multiple novel inhibitors against BRAF V600E mutation have been developed and entered into clinical trials in patients with advanced melanoma, hairy cell leukemia, and thyroid cancers." (PMID 29152094, 2017). "A major part of the current standard therapeutic strategy for melanoma includes a range of targeted treatment entities based on specific gene mutations (BRAF inhibitors), pathways or enzymes (MEK inhibitors, tyrosine kinase inhibitors) and growth factors (VEGF inhibitors)." (PMID 28567163, 2017). "Furthermore, these new immunotherapies are effective in only 45% of wild-type BRAF melanoma patients, associated with overall median survival times ranging from 11 to 20 months, with adverse events observed in 4–25% of patients." (PMID 29120401, 2017). "About half of all melanomas are associated with the BRAF V600E mutation." (PMID 29928546, 2017). "BRAF mutation rate in melanoma ranges from 40 to 60% of cases." (PMID 28039443, 2017). "Clinical and histological characteristics of BRAF V600E mutated melanomas." (PMID 28662062, 2017). "However, four additional BRAF V600E mutations in melanoma specimens were identified using the panel that should have been detected by the cobas (two failures and two false negatives)." (PMID 28196074, 2017). "Moreover, amplification of the gene encoding MET has been implicated in acquired resistance to the BRAF inhibitor vemurafenib in cultured melanoma cells." (PMID 28103611, 2017). "Melanomas that were BRAF mutated were more likely to be invasive (p = 0.03)." (PMID 28662062, 2017). "Moreover, the relationship between metabolic program and therapeutic response in BRAF-mutated melanoma is poorly understood, so we set out to probe the phenotypic relationship of metabolism and responses to the BRAF inhibitor vemurafenib." (PMID 28205616, 2017). "Accordingly, PLA experiments proved that not only CRAF but also BRAF could form complexes with NRAS in NRAS-mutated human melanoma cell lines." (PMID 28497782, 2017). "Moreover, melanoma cell lines with a BRAF gene mutation are more sensitive to sonidegib than those without a BRAF mutation." (PMID 29163356, 2017). "BRAF mutations are most commonly associated with malignant melanomas, colorectal adenocarcinomas, and papillary thyroid carcinoma and could therefore be helpful in identifying the origin of the tumor." (PMID 28343447, 2017). "In conclusion, this study reported on the patient- and tumor-related covariates that may impact BRAF mutation probability in patients with melanoma across two treatment centers in Germany." (PMID 29176861, 2017).
melanoma (continued). "Consistently, loss of MerTK sensitized melanoma cells to apoptosis upon BRAF inhibition, as determined by increased accumulation of cleaved Caspase 3, suggesting that MerTK is a critical mediator regulating cellular responses in order to antagonize apoptotic stress." (PMID 29050198, 2017). "In addition, the absence of detectable ctDNA prior to treatment (baseline) within a large cohort of melanoma patients with BRAF mutations was an independent predictor of better disease outcome." (PMID 28484715, 2017). "Therefore, this combination regimen was identified by US NCCN guideline as first-line targeted therapy of advanced melanoma patients containing BRAF V600E mutation." (PMID 29202777, 2017). "To test this, we treated the BRAF-mutated melanoma lines with PLX4720 or DMSO for 72 hours followed by flow sorting for the actively dividing FUCCI+ cells from both groups, then re-plated them in the absence of drug for 24 h and treated a second time with PLX4720." (PMID 28205616, 2017). "However, there still remain questions about what physiological role glycolysis, oxidative phosphorylation, or the mitochondria play for BRAF-mutated melanomas, particularly under the context of drug treatment." (PMID 28205616, 2017). "NRAS and its effector BRAF are frequently mutated in melanoma." (PMID 28497782, 2017). "For these reasons more recently the gold standard of therapy for BRAF mutated melanoma has become the combinations of different BRAF inhibitors (such as vemurafenib, dabrafenib and very recently encorafenib) with MEK inhibitors (such as trametinib, cobimetinib or binimetinib)." (PMID 28118616, 2017). "Most of the melanoma develops due to BRAF and NRAS mutation." (PMID 28137308, 2017). "The impact of BRAF mutation on prognosis in melanoma is currently still being investigated." (PMID 29177235, 2017). "We observed BRAF V600E mutation in 19% of nevi (n=51) and 26% of melanoma (n=42)." (PMID 28938534, 2017). "Overall, these facts indicate that oncogenic mutation of BRAF is insufficient for melanoma transformation and it may probably accompanied by one or more other genes alterations during tumor progression." (PMID 29371951, 2017). "BRAF is a mutation of a human gene encoding a serine/threonine-specific protein kinase called B-Raf in MAP kinase pathway found in approximately 50% of multi metastatic melanomas." (PMID 29195497, 2017). "In addition, BRAF mutated melanomas were less likely to reveal junctional thickening (p = 0.01) and a meshwork pattern (p = 0.02)." (PMID 28662062, 2017). "Four PR were observed in 39 patients with BRAFV600E mutation and two PR and one CR in 33 patients with BRAF‐WT melanomas and one PR in a patient with an unknown BRAF mutation status." (PMID 28719152, 2017). "Most melanomas are driven by BRAF(V600E)-activating mutations." (PMID 29214525, 2017). "Co-occurrence with telomerase reverse transcriptase (TERT) promoter mutations (found in 38% of melanomas) was observed to be more commonly associated with high-risk clinicopathologic characteristics, suggesting potential interplay of TERT promoter and BRAF mutations in melanoma evolution." (PMID 29179523, 2017). "This may be the underlying molecular mechanisms that LKB1 loss mediated in BRAF mutation melanoma cells." (PMID 29371951, 2017). "Interestingly, in the BRAF-V600E-mutated melanomas, it was reported that association of Metformin with anti-angiogenic therapies has a cumulative effect on cell killing." (PMID 28278159, 2017).
melanoma (continued). "Indeed while identification of mutations in BRAF for advanced melanoma and Hedgehog signalling for BCC has paved the road to clinical use of BRAF and smoothened inhibitors respectively, a similar direct translation has not occurred in cSCC." (PMID 28696382, 2017). "In our previous work, we showed that out of a panel of 12 melanoma cell lines, A375 was the only one carrying mutations in the BRAF oncogene where a distinct population of PD-L1+ cells could be defined." (PMID 28199980, 2017). "Clinical trials are currently underway in patients with BRAF mutation-associated melanoma by combining a BRAF-1 and IFN-α inhibitor to determine whether the combination might have greater potency than monotherapy." (PMID 28848246, 2017). "In the present study, we demonstrated that subtoxic concentrations of MC3181 are effective in reducing the invasiveness of both two BRAF-V600D-mutated melanoma cell lines (namely, WM115 and WM266.4) as well as of the BRAF-V600E-mutated human melanoma cell line SK-MEL-5." (PMID 28107182, 2017). "The HGF/SF model may not be appropriate for testing of inhibitors of mutant BRAF, the constitutive MET activity and consequent downstream activation of BRAF in HGF/SF melanomas likely precludes the genesis of BRAF-activating mutations." (PMID 28788083, 2017). "Taken together, our findings indicated that EZH2 gain may be an adverse prognostic biomarker in BRAF V600E-mutated melanoma." (PMID 29202777, 2017). "Thus, we firstly investigated if BAG3 and BRAF protein interacts in A375 melanoma cells that harbour BRAFV600E mutation." (PMID 29113311, 2017). "Indeed, BRAF mutations occur in 50–70% of all cutaneous malignant melanomas, whilst NRAS alterations only occur in 19–28% of tumours." (PMID 28637487, 2017). "Approximately 50% of melanomas harbor an active mutation in BRAF, most commonly BRAFV600E mutation." (PMID 29187213, 2017). "A main finding of additional proof-of-concept experiments was that the tumor suppressor DUSP6 could serve as a potential synthetic lethal drug target in melanoma with BRAF V600E mutations." (PMID 28423600, 2017). "The differential sensitivity to BRAF inhibition displayed by BRAF-mutated melanoma and colorectal cancers may be partly explained by the EGFR protein." (PMID 29312543, 2017). "In addition, LKB1 expression in human melanoma tissues was negatively associated with MMP-2 expression in the presence of BRAF V600E." (PMID 29371951, 2017). "Of the melanomas 80–90% show a mutation in BRAF V600E and 10–20% in BRAF V600 K." (PMID 28818062, 2017). "Thus, we have conducted a meta-analysis of randomized controlled trials comparing the efficacy and risk of all the reported adverse events in melanoma between BRAF inhibition alone and combined BRAF and MEK inhibition." (PMID 28416755, 2017). "Indeed, 66.7% (6 of 9) of the patients with BRAF-mutated melanomas in our cohort were younger than 50 years of age." (PMID 28662062, 2017). "The BRAF V600E mutation persisted, strongly indicating that the tumor was of the same origin but probably another clone, or a transformation from the primary tumor after chemoradiation with an unusual or aberrant expression profile for a melanoma." (PMID 28343447, 2017). "To investigate underlying mechanisms of acquired resistance to BRAFi we induced resistance by repeatedly exposing the parental A375 BRAF V600E mutated human melanoma cell line to increasing concentrations of the BRAFi PLX4720 or the clinically used vemurafenib." (PMID 29048432, 2017). "Our present study was undertaken to determine whether the RCM characteristics of the BRAF V600E mutated melanomas differ from the BRAF wild type melanomas." (PMID 28662062, 2017). "Furthermore, on the basis of analyses of somatic co-mutation patterns in the TCGA data sets (cBio Portal for Cancer Genomics), 9.6% of melanomas with NF1 mutations also have mutations in BRAF, NRAS or RAF1." (PMID 28637487, 2017).
melanoma (continued). "Although mutational mechanisms may differ, these studies and our data support NF1 mutations being highly relevant in melanoma subgroups that rarely harbor BRAF or NRAS mutations." (PMID 28380455, 2017). "Our findings show that inhibition of Hsp90 and BRAF signaling in human melanoma cells is, as expected, associated with induction of cell differentiation that leads to increased cell pigmentation characterised by increased tyrosinase protein expression and melanin content." (PMID 28811486, 2017). "Nine of 32 melanomas stained positive for the BRAF V600E mutation (28.1%)." (PMID 28662062, 2017). "Correlation of EZH2 gain to clinicopathologic features of BRAF V600E mutated melanomas." (PMID 29202777, 2017). "In contrast, non-V600 BRAF mutations have not been included in clinical trials with selective RAF and/or MEK inhibitors; this limitation could be due to the small proportion of patients harboring non-V600 BRAF mutations in melanoma." (PMID 28947956, 2017). "However despite major clinical benefit in melanomas with BRAF mutation, secondary resistance occurs in most patients during the first year of treatment." (PMID 28668077, 2017). "Also, a report on whole‐exome sequencing identified NF1 as the third most frequently mutated gene in melanoma after BRAF and NRAS, occasionally concurrently with other RASopathy gene mutations." (PMID 28267273, 2017). "BRAF mutation probability varied according to age and UV exposure, depending on melanoma subtype." (PMID 29176861, 2017). "Here we tested BRAF mutations in a series of 100 primary melanomas with different techniques." (PMID 28039443, 2017). "In particular, vemurafenib, trametinib, dabrafenib, and other inhibitors of the BRAF–MEK signaling pathway that is hyperactive in melanoma patients bearing BRAFV600 mutations have proven superior to traditional chemotherapy in terms of both antitumor activity and clinical outcome." (PMID 29209327, 2017). "In cases of SSM and where melanoma subtype was unknown, similar patterns were observed for the dependency of BRAF mutation probability on age and UV exposure." (PMID 29176861, 2017). "Taken together, these data strongly support the notion that evaluation of the oncogenic mutation (BRAF vs. NRAS) together with the expression of the ER subtype (ERβ vs. ERα) in melanoma patients should be taken into consideration when considering the most specific therapeutic approach to be applied." (PMID 27833586, 2016). "Furthermore, addiction to oxidative phosphorylation (OxPhos) generates drug resistance against PLX4720, a BRAF inhibitor, in BRAF-mutated melanomas." (PMID 27556512, 2016). "The acquisition of TERT promoter mutation in BRAF or NRAS mutated melanoma probably allows the re-expression of TERT leading to the immortalization process on path to melanoma development, together with other alterations such as inactivation of cyclin-dependent kinase inhibitor 2A (CDKN2A)." (PMID 27449293, 2016). "Furthermore, our findings demonstrated fisetin's ability to potentiate the anti-invasive and anti-metastatic effects of sorafenib against BRAF-mutated melanoma cells under in vitro as well as in vivo conditions." (PMID 26517521, 2016). "Significant differences in the presence of BRAF mutations were calculated for age (p < 0.001), localization of the primary tumor (p < 0.001), tumor stage at initial diagnosis (p = 0.003), type of primary melanoma (p < 0.001) and tumor thickness (p = 0.005)." (PMID 27150060, 2016). "Interestingly, BRAF mutational status in melanoma has also been shown to variably influence autophagy." (PMID 27882308, 2016). "Furthermore, on-chip analysis of BRAF mutations can also enable screening of melanoma cells within hours of sampling and circumvent the need for DNA isolation and sequencing, thereby suggesting its potential utility in clinical settings." (PMID 26815318, 2016).
melanoma (continued). "Moreover, similar results were obtained using another MEK inhibitor, trametinib, and the BRAF inhibitor vemurafenib in melanoma cell lines with BRAF mutations." (PMID 27449293, 2016). "Larkin J, Ascierto PA, Dréno B, Atkinson V, Liszkay G, Maio M, Mandalà M, Demidov L, Stroyakovskiy D, Thomas L, de la Cruz-Merino L, Dutriaux C, Garbe C, Sovak MA, Chang I, Choong N, Hack SP, McArthur GA, Ribas A. Combined vemurafenib and cobimetinib in BRAF-mutated melanoma." (PMID 27461275, 2016). "The histological study showed up a malignant melanoma with mutation of exon 15 in the BRAF gen." (PMID 27586680, 2016). "In 2014, the U.S. Food and Drug Administration (FDA) approved nivolumab and pembrolizumab for the treatment of advanced melanoma (both are limited to be approved for melanoma refractory to ipilimumab and with BRAF inhibitors, if the tumor harbors a BRAF mutation)." (PMID 26899259, 2016). "However, the association between miRNA and BRAF inhibitor resistance in melanoma remains to be elucidated." (PMID 27448964, 2016). "Furthermore, cell proliferation in melanoma cells with BRAF mutations has been reported to rely on glutamine metabolism." (PMID 27447554, 2016). "Several studies of PD-1 inhibition alone or in combination with IPI have included treatment-naïve patients with BRAF-mutated advanced melanoma who could have been eligible for our study." (PMID 27532019, 2016). "The BRAF V600E substitution is a well-characterized oncogenic mutation in cancers such as melanoma." (PMID 26989027, 2016). "Interestingly, A375 melanoma cells are carrying a similar mutation, V600E, in the activation loop of BRAF." (PMID 27339860, 2016). "It is largely admitted that BRAF mutations reprogram melanoma metabolism." (PMID 27250023, 2016). "Taken collectively, the body of data demonstrating improved response rates, meaningful improvements in PFS and OS, along with a manageable toxicity profile, establishes dual BRAF/MEK inhibition as a standard of care option for melanoma patients whose tumors harbor a BRAF V600 mutation." (PMID 26784231, 2016). "However, on the basis of our experience, we encourage the introduction of IHC as a rapid screening tool for the assessment of BRAF status in melanoma patients in routine diagnostic procedures." (PMID 27863476, 2016). "BRAF V600K mutation carriers have poor long term prognosis when compared to V600E mutated melanoma." (PMID 26989536, 2016). "MiR-193a, miR-338, and miR-565 were down-regulated in melanomas with BRAF mutations." (PMID 26646588, 2016). "A melanoma with a BRAF-V600E mutation was resected from the right chest wall of a patient." (PMID 27835903, 2016). "Dabrafenib was approved by the US FDA in May 2013 for the treatment of patients with advanced melanoma that contains the V600E mutation of BRAF at a dose of 150 mg orally twice a day." (PMID 26767073, 2016). "In this investigation, we aimed to determine whether fisetin can potentiate the anti-invasive and anti-metastatic effects of sorafenib in BRAF-mutated melanoma." (PMID 26517521, 2016). "Interestingly, in this cohort, ZEB1 expression was higher in BRAFV600 or NRASQ61R‐mutated melanomas compared to BRAF/NRAS WT tumors, which corroborates the involvement of the MAPK pathway in the regulation of ZEB1." (PMID 27596438, 2016). "Mutations in the BRAF gene have been reported in approximately 50% of the patients with melanoma." (PMID 27200295, 2016). "CCS also lack BRAF mutations which are commonly found in melanoma." (PMID 27375743, 2016). "Although both BRAF and CRAF are expressed and active in melanoma signaling processes, only BRAF shows a high mutation frequency (approximately 50% of melanomas), whereas CRAF mutations are rare and so far have not been demonstrated to generate an alternative activated oncogene." (PMID 27273450, 2016).